IL12B (interleukin 12B)
Diseases named in the same sentence as IL12B in open-access papers (continued):
Sharing a sentence is not in itself a finding about the gene and the disease.
infection (75 papers, 2008 to 2025). The state of being infected such as from the introduction of a foreign agent such as serum, vaccine, antigenic substance or organism. "We found the expression of il23a (encoding IL23p19) to be transiently upregulated on day 3 post infection (PI), alongside il12b (encoding IL12p40), while il12a (encoding IL12p35) was induced only by day 6 PI." (PMID 25761673, 2015). "Other pro-inflammatory factors like IRF5, IL-12B, IL-1RN, IL-22, IL-8, and IL-33 significantly increased at 48 hpi in weaned piglets compared to newborn piglets after infection." (PMID 40589734, 2025). "The particular role of Il12b in this process was revealed when both infection and IFNG activation are removed from the equation, i.e., the pre-stimulated, activated and infected macrophages are compared to activated and infected macrophages (M1-Ita vs. M1)." (PMID 37235312, 2023). "The Tc/EOW group produced a response with a predominance of IFN-γ and IL-12B, and significantly high IL-1β (p = 0.0152) and IL-10 (p = 0.0247), showing the highest concentration at the time of infection of this last cytokine." (PMID 37242721, 2023). "Next, we revealed that at the early time point after infection (2 h.p.i.), robust induction of the cytokines, including Ifnb1, Tnfa, Il12b, and inflammasome genes Nlrp3 was obtained, which is consistent with a previous study." (PMID 35604097, 2022). "While some expression patterns remained elevated during infection, by day 5 there was increased Il-12a, Il-12b, Il-6, Cd80, and Cxcl11 expression that corresponded with elevated Il-15 levels in young adult H1N1 and H3N2 infected lung." (PMID 34829979, 2021). "VLV had a broader impact on gene expression in DCs after infection, upregulating genes related to inflammation (such as Ccl5, Ccl4, and IL12b), but also downregulating other genes." (PMID 34811393, 2021). "An important gene for growth during stress, CHORDC1 associated with post-infection growth rate was identified as a positional candidate gene, as well as other immune related genes, including VAV2, IL12B, DUSP1, and IL17B." (PMID 32849779, 2020). "The gene expression levels of Tnfa and Il12b and the protein levels of IL-6 in the livers of μMT mice 6 weeks after infection were significantly higher than those in WT mice." (PMID 31194740, 2019). "Levels of TNF-α and CCL2 were significantly elevated from pre-clinical to early-stage infection, and IL-6, IL-12b, CCL3, CCL12, and ISG15 levels were significantly elevated from pre-clinical to late-stage infection." (PMID 31790513, 2019). "Further, in THP1 cells, a human monocytic cell line, IL-12B gene expression was downregulated immediately after in vitro infection with MAP." (PMID 31788366, 2019). "Remarkably, cells isolated from T. gondii seropositive individuals up-regulated IL-12b (i.e., IL-12p40) mRNA significantly stronger in response to in vitro infection than those from seronegative control individuals (p < 0.001; ANOVA)." (PMID 31316920, 2019). "We demonstrated that L. major FV1 induced approximately 15-fold greater amounts of IL12B than L. major LV39c5 at 8 hours post infection, the optimal time for peak IL12B mRNA expression following L. major infection." (PMID 26630499, 2015). "There was little change in the mRNA levels for the Th1 cytokines, IL-12a and IL-12b, except in the bone marrow where levels were reduced following infection." (PMID 26244502, 2015). "Our results demonstrate that hDC infection with the LPG-null L. major FV1 lpg1− mutant resulted in significantly diminished IL12B mRNA, relative to FV1 WT parasites, indicating that LPG is essential for stimulating host IL12 production." (PMID 26630499, 2015). "The expression of mRNA encoding several interleukins was also induced in the infected mouse uterus at 28 days post-infection, including Il1b, Il12a, Il12b, Il16, Il18, and Il27." (PMID 26779389, 2015).
infection (continued). "We demonstrated that FV1 lpg1− induces significantly less TNF mRNA compared to WT or FV1 lpg1−/+LPG1 add back infections, similar to the pattern of IL12B expression." (PMID 26630499, 2015). "The levels of histone H3-acetylation on IL-12B promoter was found to decrease as a consequence of infection with live, virulent MTB." (PMID 26697414, 2015). "While MHV68 latency did not rescue the induction of Tnf or Il6 transcripts in HOIL-1 KO mice following infection with Listeria, Il12b transcript levels were increased approximately twofold, and were comparable to levels in control mice." (PMID 25599590, 2015). "Albeit at higher expression levels than FV1 WT, FV1 lpg2− induced a similar kinetic IL12B mRNA response that declined by 24 hrs post infection." (PMID 26630499, 2015). "To assess the pathways involved in the regulation of IL12 by LPG, we utilized STEM and identified 233 genes that exhibited expression patterns similar to IL12B in response to infection with FV1 WT, FV1 lpg1−, and FV1 lpg2−." (PMID 26630499, 2015). "First, we showed that, for this strain, infection with metacyclic promastigotes induces a high IL12B response, compared to procyclic promastigotes and amastigotes, consistent with prior studies." (PMID 26630499, 2015). "To explore the role of LPG on the IL12 response elicited from L. major infected hDCs, we quantified the relative amount of IL12B mRNA in hDCs after 8 hours of infection with FV1 WT, FV1 lpg1−, and FV1 lpg1−/+LPG1 parasites." (PMID 26630499, 2015). "In our results, mRNA for Il12 subunit alpha (Il12a) and subunit beta (Il12b) was induced at 28 days after infection." (PMID 26779389, 2015). "THP-1 cells induced elevated IFNα mRNA expression under DEN-2 infection, however, PMA-differentiated THP-1 cells elicited higher IL12B mRNA expression and protein levels under the same infection." (PMID 23216989, 2012). "Consistent with previous results, LPS also induced higher levels of Il12b in Nfkb1−/− cells than in control cells following infection with vector alone." (PMID 22427889, 2012). "We showed that increase of Th1 cytokine, IL12B expression in differentiated THP-1 cells was found in DEN-2 infection." (PMID 23216989, 2012). "Down-regulation of Il13ra1 combined with up-regulation of Il12b (30.2-fold), suggested switch to a pro-inflammatory response by 4 hrs post H37Rv-infection." (PMID 22039457, 2011). "In both cases, individuals carrying the Il12b CC haplotype had an increased probability of infection." (PMID 22039363, 2011). "Namely, CD5, CD8A, CD6 and CD244, C-C and C-X-C motif chemokines (CXCL5 CXCL6, MCP-4, and CCL20), as well as CD40, PDL-1, CUB domain-containing protein 1 (CDCP1) and interleukin-12B (IL-12B) were elevated in the late infection group compared to the unexposed group." (PMID 41510260, 2025). "A significant decrease in representative pro-inflammatory factor (IL12B) expression with prolonged infection was observed while anti-inflammatory transforming growth factor beta-1 (TGF-β1) expression was continuously high during infection at 10°C." (PMID 35197977, 2022). "In a previous study, we had shown that infection of human macrophages with virulent M. tuberculosis causes the levels of histone deacetylase 1 (HDAC1) to increase significantly and repress expression of the IL-12B gene." (PMID 33627504, 2021). "The ability of Leishmania to selectively suppress IL12 production, as first established by using murine macrophages, occurs through the transcriptional inhibition of the IL12B promoter and is one immune evasion strategy employed by parasites to establish infection." (PMID 26630499, 2015). "Indeed, also in our animal facility these mice died from infection, as did (il12b−/−>il12b−/−) BM chimeras, while animals with p40-proficient donor or recipient genotype survived." (PMID 25761673, 2015).
infection (continued). "In contrast, hDC infections with FV1 lpg2- displayed increased IL12B expression, suggesting other PG-related/LPG2 dependent molecules may act to dampen the immune response." (PMID 26630499, 2015). "Here we report that infection of macrophages by live virulent MTB induces upregulation of HDAC1 expression which in turn is effectively employed to deacetylate histone H3 at the promoter of IL-12B gene." (PMID 26697414, 2015). "Phagocytosis of the infecting Mtb and upregulation of TLR-2 and TLR-4 would result in the early production of IL-12, thereby contributing to the activation of lymphoid cells, consistent with our observation of elevated IL12B expression at 2 weeks post-infection." (PMID 23448601, 2013). "The relative quantification analysis showed a significant increase in gene transcription by 15 min following H37Rv-infection for the Ccl24 (26.5 fold [P<0.001]), Pparg (10.5 fold [P = 0.003]), Clec4a2 (23.2 fold [P<0.001]) genes and the Il12b (12.2 fold [P = 0.002]) gene." (PMID 22039457, 2011). "Six genes belonging to the two most significantly over-represented biological processes at the 15 min post H37Rv-infection ‘Immune system response’ (Ifnb1, Il12b, Ccl24, Pparg, and Clec4a2) and ‘Response to stimulus’ (Il13ra1) were selected for verification by RT-QPCR analysis." (PMID 22039457, 2011). "Similarly, in TMEV-infection, microglia exclusively expressed Il12b and Il12rb1." (PMID 34311763, 2021). "We found the upregulation of IL-12A, IL-12B, and TNF, suggesting a possible involvement of B cells in shaping the splenic type-1 cytokine environment in Ot infection." (PMID 37146079, 2023). "Our results indicate that the expression of IL6, IL12B, IL1R2, IL23R, IL12RB1 and IL12RB2 increased after DTMUV infection." (PMID 35585616, 2022). "Particularly, infection upregulated the cytokines IFN-γ, IL-12b, and IL-2 (126-, 44-, and 18-fold change, respectively) and the T-cell chemoattractants CCL3 and CCL5 (23- and 16-fold change, respectively)." (PMID 34381739, 2021). "Specifically in the module, we find genes induced in response to infection such as IL1B, TNF, IL6, IL12B, NFKBIA, JUN, and MAP3K8, which are related to Toll-like receptor signalling (Appendix B)." (PMID 33498280, 2021). "In susceptible, BALB/cAnN mice, a 12-fold increase in IL-4 expression was observed on day 5 post-infection, while more modest increases were observed for the expression of IFN-γ and IL-12b." (PMID 33928043, 2021). "IMPORTANCE Following infection with M. tuberculosis, levels of HDAC1 go up in macrophages, and it is recruited to the promoter of IL-12B where it hypoacetylates histone H3, leading to the downregulation of the gene." (PMID 33627504, 2021). "Expression of IFNG, IL17A, IL12B, and IL27 was analyzed with PBMCs and PP cells isolated at 28 days post-infection and re-stimulated with individual recombinant MAP proteins." (PMID 33329565, 2020). "Thus, we determined whether local C5aR1 activation affects the transcription of IFN-γ (Ifng) in the spleen and brain as well as IL-12p35 (Il12a), IL-12p40 (Il12b), IL-18 (Il18), and iNOS (Nos2) in the brain of T. gondii-infected animals on day seven after infection using RT-qPCR." (PMID 32733463, 2020). "With the infection mouse model above, we found that EDL933(ΔTir + HA-Tir) induced lower Tnf, Il6, Il12b, and Il1b than EDL933ΔTir, which was nearly reversed by EDL933(ΔTir + Y490F, Y519F) in the colons and spleens." (PMID 31130074, 2019). "Infection with metacyclic, infective stage, L. major or purified LPG induced high levels of IL12B subunit gene transcripts in hDCs, which was abrogated with FV1 lpg1- infections." (PMID 26630499, 2015). "We observed that following infection with live MTB H37Rv at 24 h PI, there was an increased recruitment of HDAC1 to the promoter of IL-12B gene." (PMID 26697414, 2015). "Surprisingly, Il12b transcript levels were similar in HOIL-1 KO mice, with a significant difference being detected at only 6 hr after infection." (PMID 25599590, 2015).
infection (continued). "Both genes encoding IL-12 had significantly increased transcript levels at the site of infection in our model (Il-12a Day 1 LFC 2.84; Day 4 LFC 2.00; Il-12b Day 4 LFC 2.23, Day 7 LFC 4.29)." (PMID 25901897, 2015). "By 2 hours post-infection, FV1 lpg2− mutant infected hDCs induced slightly more IL12B compared with FV1 WT infected DCs." (PMID 26630499, 2015). "Early after infection of C57BL/6 mice with Mtb real time RT-PCR of lung homogenates was conducted to compare gene expression of Il22 with the expression of Il17a, Il17f, Il12b, and Il23p19." (PMID 23460846, 2013). "Consistent with this, il12a, il12b, ifng, il6, il17a mRNA expression were considerably increased in the brains of P. berghei ANKA-infected Alox5-KO vs. WT mice at 5 days after infection." (PMID 23613965, 2013). "While e.g. IL12B expression was increased right after infection and throughout the entire experiment, IL10 and IL12A showed lower expression in early infection stage compared to E. coli K12 stimulated MDMs (P<0.005, unpaired t test)." (PMID 21629653, 2011). "Concomitantly, genes involved in inflammatory and interferon-related responses, including IFN-γ, IL-12b, STAT1, STAT3, IL-6, TNF-α, CXCL9, CXCL10, and CXCL5, were significantly upregulated, indicating a strong pro-inflammatory environment during peak infection." (PMID 40630939, 2025). "Individuals with polymorphisms in loci containing IL6, IL10, FCN2, RNASE3 and multiple Th17 pathway genes such as IL12B and IL17B had varying worm burden, indicating that these loci may play a role in determining infection intensity." (PMID 38033168, 2023). "Notably, analysis of cytokine/chemokine expression (Olink) identified a significant increase of activators of cytotoxic NK cells, including IL-12B and the immunoregulatory signaling molecule CD244, in less severe infection." (PMID 37327781, 2023). "At 7th day post challenge, TLR5, TLR7, il6, il1b, and IL12B were still highly expressed, suggesting that TLR may play a role in both early and late stages of infection." (PMID 36439120, 2022). "Following infection, ZBTB25 and Sin3a were found to be recruited to the IL-12B promoter at 24 hpi." (PMID 33627504, 2021). "Moreover, Nc-Spain7 infection induced lower ROS production, IL10 and IL12B expression by MØs than Nc-Spain1H infection, which also resulted in decreased IFN-γ release by activated lymphocytes." (PMID 32711550, 2020). "Remarkably, CSF2 (encoding granulocyte-macrophage colony-stimulating factor), IL-6 (interleukin-6), IL-12B (interleukin-12 subunit beta), CSF3 (granulocyte colony-stimulating factor), and TNF (tumor necrosis factor) were extremely highly expressed upon infection with WT V. vulnificus (log2 FC > 8)." (PMID 32817457, 2020). "DC isolated early after infection of pigs with either of the two CSFV strains showed prominent upregulation of CCL5, CXCL9, CXCL10, CXCL11, and XCL1, as well as of the cytokines TNFSF13B, IL6, IL7, IL12B, IL15, IL27." (PMID 32733474, 2020). "The infection results showed that EDL933(ΔTir + Y490F) and EDL933(ΔTir + Y519F) induced much higher production of Tnf, Il6 and Il12b than the EDL933(ΔTir + HA-Tir) strain in mouse primary peritoneal macrophages, and EDL933(ΔTir + Y490F, Y519F) induced even higher cytokine production." (PMID 31130074, 2019). "The genes with strongest induction included chemokines (e.g. CXCL11, 84-fold; CXCL10, 18-fold; CXCL9, 9-fold; CCL2, 9-fold) and cytokines (e.g. IL6, 54-fold; IL12B, 10-fold; IL1B, 9-fold;) etc. consistent with the infection of host phagocytes with Mtb reported earlier by us." (PMID 28880895, 2017). "The gene expression of Th1 cytokines (IFN-γ and IL-12B) and IL-10 showed no significant change during early infection." (PMID 29216911, 2017). "To determine whether the enhanced IL12B production observed following infection with L. major FV1 metacyclic promastigotes was an LPG-dependent response, we first assessed the role of purified LPG on the hDC IL12B response." (PMID 26630499, 2015).
infection (continued). "It is possible that infection with FV1 lpg1− reduces the amount of IRF8, which in turn inhibits the capacity of other transcription factors, such as IRF1, to form heterodimeric complexes that bind the IL12B promoter." (PMID 26630499, 2015). "Higher levels of IL12B mRNA but not IFNα mRNA were induced in PMA-treated THP-1 cells after 24 h DEN-2 infection." (PMID 23216989, 2012). "In conclusion, the gene-expression signature predominant in livers of BALB/c mice 10 days after infection with L. infantum is characterized by the overrepresentation of IL12-mediated signaling events (FDR=0.003) with the strong upregulation of Il12rb2, Ifng, Nos2, Il12rb1, and Il12b." (PMID 34281214, 2021). "As expected, knockdown of HDAC1 significantly increased the levels of IL-12B expression in macrophages infected with live MTB, thus confirming the observation that downregulation of IL-12p40 upon infection with live MTB was indeed a result of infection-induced HDAC1 expression." (PMID 26697414, 2015). "Interestingly, the IL12B mRNA expressing levels were also kinetically induced and dose-dependent in PMA-differentiated THP-1 cells and reached its maximum induction at 24 h post-infection of DEN-2." (PMID 23216989, 2012). "However, IL12A and IL12B, which are thought to also favor Th1 cell development, did not change their expression level during infection." (PMID 18811943, 2008). "Although IRF1 and IRF8 are known to cooperatively regulate IL12B gene transcription, we report that the FV1 lpg1− mutant does not affect IRF1 expression compared to WT at 8 hours post-infection." (PMID 26630499, 2015). "To delineate the effect of FV1 lpg1− and/or FV1 lpg2− on the upstream transcriptional features that regulate IL12B expression, we assessed IRF1 expression in hDCs and observed that infection with FV1 mutants up-regulated IRF1, but not significantly more compared to WT induced levels." (PMID 26630499, 2015).